SOD2 (superoxide dismutase 2)
Description:
Destroys superoxide anion radicals which are normally produced within the cells and which are toxic to biological systems.
Synonyms: GC1; IPOB; MnSOD; GClnc1; lncRNA-GC1; IPO-B; MVCD6; Mn-SOD
Tractability: Small molecule: a structure with a bound ligand is known; it has a high-quality binding pocket. PROTAC: UniProt records ubiquitination sites on it; ubiquitination databases record sites on it; its protein half-life has been measured.
Target class: Enzyme; Oxidoreductase
Safety:
Unwanted effects reported when the protein is acted on. In parentheses: how it was acted on, where the effect was seen, and who reports it.
drug toxicity (source: ClinPGx)
hepatotoxicity (source: ClinPGx)
heroin dependence (source: ClinPGx)
neuropathy (source: ClinPGx)
Gene: Protein-coding gene on chromosome 6 (159,669,069 to 159,762,529, reverse strand). Ensembl gene ENSG00000291237.
Subcellular location: Mitochondrion matrix
Subcellular location (Human Protein Atlas): Mitochondria
Pathways (Reactome):
Cellular responses to stimuli: Detoxification of Reactive Oxygen Species; Mitochondrial unfolded protein response (UPRmt)
Disease: Deregulated CDK5 triggers multiple neurodegenerative pathways in Alzheimer's disease models
Gene expression (Transcription): FOXO-mediated transcription of oxidative stress, metabolic and neuronal genes
Immune System: Gene and protein expression by JAK-STAT signaling after Interleukin-12 stimulation
Organelle biogenesis and maintenance: Transcriptional activation of mitochondrial biogenesis
Gene Ontology:
Molecular function: identical protein binding; manganese ion binding; protein binding; superoxide dismutase activity; DNA binding; enzyme binding; metal ion binding; oxidoreductase activity; oxygen binding
Biological process: cellular response to oxidative stress; intracellular oxygen homeostasis; negative regulation of cell population proliferation; negative regulation of neuron apoptotic process; negative regulation of oxidative stress-induced intrinsic apoptotic signaling pathway; negative regulation of vascular associated smooth muscle cell proliferation; positive regulation of cell migration; positive regulation of phenotypic switching; positive regulation of vascular associated smooth muscle cell apoptotic process; positive regulation of vascular associated smooth muscle cell differentiation; protein homotetramerization; regulation of transcription by RNA polymerase II; removal of superoxide radicals; response to superoxide; superoxide metabolic process; acetylcholine-mediated vasodilation involved in regulation of systemic arterial blood pressure; regulation of blood pressure; release of cytochrome c from mitochondria; cellular response to ethanol; hydrogen peroxide biosynthetic process; hydrogen peroxide metabolic process; negative regulation of apoptotic process; negative regulation of membrane hyperpolarization; positive regulation of hydrogen peroxide biosynthetic process; response to activity; and 16 more
Cellular component: extracellular exosome; mitochondrial matrix; mitochondrion; cytoplasm; mitochondrial nucleoid
Homologues: Orthologues: macaque SOD2 (98% identical), chimpanzee SOD2 (96% identical), guinea pig SOD2 (92% identical), dog SOD2 (91% identical), mouse Sod2 (89% identical), pig SOD2 (89% identical), rat Sod2 (87% identical), tropical clawed frog sod2 (80% identical), zebrafish sod2 (80% identical), Caenorhabditis elegans sod-2 (61% identical), Caenorhabditis elegans sod-3 (59% identical), Drosophila melanogaster Sod2 (57% identical).
Diseases named in the same sentence as SOD2 in open-access papers:
SOD2 is named in the same sentence as 574 diseases in open-access papers, as found by Europe PMC text mining. Sharing a sentence is not in itself a finding about the gene and the disease. The quoted sentences say what the papers report.
breast carcinoma (167 papers, 2004 to 2025). "Transcription factors such as specificity protein 1 (Sp1) and AP-2 regulate SOD2 transcription, and silencing of AP-2 by hypermethylation has been linked to MnSOD upregulation in aggressive breast cancer." (PMID 40722952, 2025). "In contrast, high expression levels of SOD2 are associated with a worse prognosis in patients with breast cancer." (PMID 40244057, 2025). "Almost 190 genetic variations variants have been described in the SOD2 gene until now, and have been involved in breast cancer, diabetes mellitus, dyslipidemia, and other diseases." (PMID 36286017, 2022). "Kaplan–Meier survival analysis revealed that higher expression of PPARα and SOD2 was associated with improved survival of breast cancer patients." (PMID 35534547, 2022). "MAPKs, EGF, Rac, Src signaling pathways are thought to be potentially related to SOD2-associated breast cancer progression." (PMID 35203574, 2022). "Reported studies have been revealed that SOD2 has been linked with the energy metabolism of colorectal cancer, oxidative stress in endocrine cancer, and stem cell reprogramming in breast cancer." (PMID 34872548, 2021). "Contrary to this, other studies have demonstrated that the wild-type alanine phenotype carries a greater risk of prostrate, ovarian and breast cancer, suggesting a pro-tumorigenic role for fully-functional SOD2 in these cancers." (PMID 29099803, 2017). "This has been described to underlie the high SOD2 expression observed in aggressive breast cancer cells." (PMID 29099803, 2017). "Loss of SIRT3 activity and hyperacetylation of SOD2 have been reported in many cancers including breast cancer, hepatocellular carcinoma, glioma and B cell malignancies." (PMID 29099803, 2017). "The rs4880 G allele (located within super superoxide dismutase 2-SOD2-gene) has been correlated with lower survival in breast cancer patients treated with chemotherapy (p = 1E−3)." (PMID 26801900, 2016). "We used meta-analytic techniques to compare our findings with published studies on the association of SOD2 and breast cancer survival." (PMID 24498107, 2014). "Researchers have suggested that findings from the individual studies should be assembled in a meta-analysis in order to better define the association of SOD2 polymorphisms and outcomes in patients with breast cancer." (PMID 24498107, 2014). "We examined the association of SOD2 genotype and breast cancer recurrence (BCR) among patients treated with cyclophosphamide-based chemotherapy (Cyclo)." (PMID 24498107, 2014). "Nonetheless, as in our study, they found a near-null association between the SOD2 polymorphism and the effectiveness of chemotherapy, as measured by breast cancer recurrence (hazard ratio = 0.66, 95% CI = 0.34, 1.29)." (PMID 24498107, 2014). "Mutation in SOD2 gene has been described in breast carcinoma and mutation or methylation at the promoter region of SOD2 gene is shown to down-regulate manganese superoxide dismutase (MnSOD), a putative tumor suppressor in cancer cells." (PMID 24690091, 2014). "We were unable to extract an effect estimate from a study in Czech breast cancer patients, which reported an increased risk of recurrence among patients homozygote for the SOD2 polymorphism." (PMID 24498107, 2014). "A null association was also reported in a Chinese study of breast cancer patients, in an Italian study focused on MnSOD protein expression and breast cancer survival, and in studies evaluating the effect of SOD2 on survival in patients with other cancers." (PMID 24498107, 2014). "Consistent with our findings, many studies reported that the Ala-SOD2 leads to increased risk of prostate and breast cancer, and we suggest that one mechanism may be induction of higher EMT by Ala-SOD2." (PMID 33535682, 2021). "As SOD2 rs4880 was marginally associated with breast cancer risk in Caucasians, this could contribute to the observed deviation from HWE." (PMID 33425072, 2020).
breast carcinoma (continued). "Interestingly, transcriptional activating H3 histone marks are associated with increased SOD2 expression in aggressive breast cancer." (PMID 29099803, 2017). "Importantly, activation of the SIRT3 axis of the UPRmt was seen in primary breast cancer patients and high expression, using SOD2 as a marker, was significantly associated with worse disease-free survival." (PMID 28798902, 2017). "In addition to DNA methylation, transcriptional suppression of SOD2 in breast cancer cells is associated with repressive histone marks (decreased H3K4me2 and H3K9ac) and condensed chromatin structure in the regulatory regions." (PMID 29099803, 2017). "The functional rs4880 alanine-to-valine (C > T) single amino acid change has been found to influence enzyme activity with valine (T) associated with reduced SOD2 activity in human breast cancer and hepatoma cell lines; contradictory findings have also been reported." (PMID 27099827, 2016). "A polymorphism in its encoding gene (SOD2: Val16Ala rs4880) may confer poorer breast cancer survival, but data are inconsistent." (PMID 24498107, 2014). "A study has suggested that higher antioxidant activity due to an Ala variant of rs4880 in SOD2 may cause poorer survival following cyclophosphamide-containing breast cancer chemotherapy." (PMID 24348785, 2014). "An analysis of SOD2 expression conducted in several tumor samples including lymphoma; glioblastoma; and bladder, colorectal, oral, lung, kidney, ovarian, penile, and breast cancers have often associated its upregulation with metastasis and poor disease outcome." (PMID 34062984, 2021). "Therefore, we conducted a population-based case-control study among women treated with cyclophosphamide-based chemotherapy (cyclophosphamide-epirubicin-5-fluorouracil – CEF) in Denmark to evaluate the effect of the SOD2 polymorphism on breast cancer recurrence." (PMID 24498107, 2014). "TPT-NCSe (500 nM) decreases SOD1 mRNA, increases SOD2 mRNA in MCF-7 breast cancer cells, and increases SOD2 mRNA in MDA-MB-231 cells." (PMID 38227157, 2024). "No relevant data are available in literature on the effect of AtRA, a cognate ligand of RARs, on the SOD1 or SOD2 expression in human breast cancer cell lines." (PMID 38227157, 2024). "According to the hierarchical clustering analysis of 52 breast cancer cell lines, SOD2 and GPX8 genes were part of the mesenchymal gene signature and co-clustered with ZEB1, VIM, and SNAI2." (PMID 38172210, 2024). "Jabir F.A., Hoidy W.H. Pharmacogenetics as personalized medicine: associationinvestigation of SOD2 rs4880, CYP2C19 rs4244285, andFCGR2A rs1801274 polymorphisms in a breast cancer populationin Iraqi women." (PMID 39027127, 2024). "Human breast carcinoma ZR-75-1 cells were transfected with an adenoviral construct containing the cDNA for SOD2 (AdMnSOD) to increase SOD2 expression." (PMID 38542138, 2024). "The NuRD (MTA1) complex promotes EMT through transcriptional repression of peroxisome proliferator-activated receptor α (PPARα) and superoxide dismutase 2 (SOD2) in breast cancer." (PMID 39154024, 2024). "In parallel, both miR‐335 downregulation and SOD2 overexpression abrogated the antitumor effects of ZNF‐148 deficiency on proliferation and pyroptosis in breast cancer cells." (PMID 37909239, 2023). "The present study identified a ZNF‐148/miR‐335/SOD2 feedback loop that regulates breast cancer development, thereby suggesting ideal targets for breast cancer treatment in the clinic." (PMID 37909239, 2023). "Acetylated SOD2 promoted hypoxia signal transduction by increasing mitochondrial activity and promoting reprogramming of breast cancer stem cells." (PMID 37759978, 2023). "Variations in the SOD2 and SOD3 genes can participate in susceptibility to breast cancer, chronic obstructive pulmonary disease in adults and children, preeclampsia, insulin resistance, type 2 diabetes, and arterial hypertension." (PMID 38133349, 2023).
breast carcinoma (continued). "In aggressive breast cancer cell lines, knockdown of the mitochondrial superoxide dismutase (MnSOD/SOD2) gene has been shown to reverse EMT, indicating that hydrogen peroxide produced by MnSOD in mitochondria promotes EMT." (PMID 37009472, 2023). "By detecting the expression of related genes and proteins, the mechanism of the promising candidate increasing intracellular ROS and inducing apoptosis of breast cancer cells through the c-MYC/SOD2 pathway was clarified." (PMID 38275631, 2023). "Elsewhere, breast cancer cells exhibit nuclear SOD2 as well as chromatin decondensation at genes involved in self renewal, dedifferentiation, and stemness reprogramming, resulting in increased metastatic potential." (PMID 37228489, 2023). "Our findings indicated that ZNF‐148 promotes breast cancer progression by triggering miR‐335/SOD2/ROS‐mediated pyroptotic cell death and aid the identification of potential therapeutic targets for breast cancer." (PMID 37909239, 2023). "Taken together, we concluded that ZNF‐148 acts as an oncogene to facilitate breast cancer pathogenesis, and knockdown of ZNF‐148 triggers oxidative stress‐mediated pyroptotic cell death in breast cancer by downregulating SOD2 in a miR‐335‐dependent manner." (PMID 37909239, 2023). "Overexpression and downregulation of ZNF‐148 in breast cancer cells demonstrated that ZNF‐148 positively regulated SOD2." (PMID 37909239, 2023). "High SOD2 expression was detected in 80% of breast cancer patients and was positively correlated with MCTS1 (p < 0.001)." (PMID 35017469, 2022). "During our studies, we proved that drug-induced tumor cell death increases the plasma levels of SOD2 correlating with the response to neoadjuvant therapy in breast cancer patients." (PMID 36010852, 2022). "Impaired SOD2 activity has been related to several diseases such as cancer, particularly ovarian and breast cancer, diabetes mellitus, and neurodegeneration, including AD." (PMID 36286017, 2022). "In breast tumor xenograft models, injection of Cu-ZnSOD or SOD2 adenoviral vectors in combination with BCNU significantly reduced breast cancer cell growth and increased nude mice survival." (PMID 35164076, 2022). "In summary, we elucidated that HIF-2α remodeled stemness in breast cancer and conferred chemoresistance to BCs via SOD2-mtROS-PDI/GRP78-UPRER axis." (PMID 35301432, 2022). "Li confirmed that upregulation of SOD-2 in breast cancers was suggested to function as a tumor suppressor gene." (PMID 35368886, 2022). "From the Oncomine cancer microarray database, we found that MCTS1 and SOD2 expression was positively correlated in breast cancer patients (p < 0.0001)." (PMID 35017469, 2022). "The overexpression of SOD2 in breast cancer MCF-7 cells increased the expression of p21 and E-cadherin and decreased the expression of Cyclin D1 and MMP-2, suggesting that SOD2 inhibits the proliferation, migration, and invasion of MCF-7 cells." (PMID 36142828, 2022). "Further characterization of SOD2 mRNA levels was conducted with breast cancer cDNA arrays (OriGene)." (PMID 35017469, 2022). "In breast cancer, SOD2 is epigenetically regulated, where SOD2 expression is repressed primarily due to the hypo acetylation of histone proteins." (PMID 36009568, 2022). "PPARα and SOD2, which inhibited breast cancer bone metastasis, were found to be the target genes of the RUNX2/NuRD(MTA1)/CRL4B complex." (PMID 35534547, 2022). "On UPRmt activation, the intermembrane space (IMS) found SOD1 found to be increased than SOD2 in breast carcinoma cells." (PMID 34717757, 2021). "This is consistent with previous findings which similarly showed higher SOD2 expression in three breast cancer cell lines expressing Ala-SOD2 compared to three breast cancer cell lines with Val-SOD2." (PMID 33535682, 2021). "It is reported that DDB2 transcriptional regulates IκBα and SOD2 in breast cancer cells, and Snail, Zeb1 and VEGF in colon cancer." (PMID 33557942, 2021).
breast carcinoma (continued). "The enhancer function of SOD2 in cellular migration and metastasis is further supported by data demonstrating the correlation of SOD2 expression and phosphorylation of breast cancer anti-estrogen resistance protein 1 (BCAR1), also known as p130Cas." (PMID 29478325, 2019). "In conjunction with the NAPDH oxidase NOX4, SOD2 contributes to breast cancer progression at late stage III by promoting AMPK phosphorylation at Thr172." (PMID 29478325, 2019). "The expression of SOD2 is altered in various types of cancers, including squamous cell carcinoma, lymphoma, leukemia, sarcomas, colon cancer, breast cancer, esophageal cancer, pancreatic cancer, liver cancer, lung cancer and central nervous system cancers." (PMID 31795319, 2019). "Previous studies have shown that during transformation, breast cancer cells predominately expressing SOD2 to expressing SOD1 as the primary superoxide dismutase isoform." (PMID 29891006, 2018). "A binding site for DDB2 has been identified at position −230, and it is thought that DDB2 represses SOD2 transcription in breast cancer cells through interaction with AP-2, inhibiting the recruitment of Sp1 to the promoter." (PMID 29099803, 2017). "For example, hypermethylation of the AP-2 gene decreases AP-2 expression in aggressive breast cancer cells, where high SOD2 expression is often observed relative to non-invasive breast cancer cells." (PMID 29099803, 2017). "Not only do SOD2 levels increase in response to cytokines and growth factors, the Lu group has demonstrated that breast cancer cells elevate SOD2 expression under anchorage independence in an NF-κB-dependent manner." (PMID 29099803, 2017). "Recently, SIRT3 was reported to be decreased in 87% of breast cancers, resulting therefore in a decrease in the activity of SOD2 and an elevation in ROS." (PMID 24955214, 2014). "Additionally, invasive breast cancer cell lines exhibit higher SOD2 activity than non-invasive cell lines." (PMID 40244057, 2025). "Based on these findings, we hypothesized that miR‐335 may be the “bridge” to combine ZNF‐148 and SOD2 and that ZNF‐148 may be involved in breast cancer progression by targeting miR‐335/SOD2 signaling." (PMID 37909239, 2023). "In addition, we investigated the role of the ZNF‐148/miR‐335/SOD2 pathway in regulating breast cancer pathogenesis and found that knockdown of ZNF‐148 suppressed cell viability by downregulating SOD2 by sequestering miR‐335." (PMID 37909239, 2023). "Similarly, in breast cancer, it was also confirmed that the expression of MnSOD can be inhibited by histone deacetylation and hypomethylation, thus forming a closed chromatin structure at SOD2, inhibiting the function of transcription factors." (PMID 37759978, 2023). "Moreover, decreased SIRT3 activity and acetylation of SOD2 have been reported in various cancers such as breast cancer and hepatocellular carcinoma." (PMID 37533102, 2023). "SOD2 is a potential marker of metastatic progression of breast cancer." (PMID 35203574, 2022). "Functional experiments demonstrated that RUNX2/NuRD(MTA1)/CRL4B complex could promote EMT and bone metastasis by inhibiting the expression of PPARα and SOD2 in breast cancer." (PMID 35534547, 2022). "Moreover, there is a switch from SOD2 to SOD1 during the transformation process in breast cancers, and SOD2 is downregulated in malignant breast cancer cells compared to their normal cell counterparts." (PMID 36009568, 2022). "Furthermore, the expression of PPARα and SOD2 was explored in normal and breast cancer tissues from published datasets (GSE42568, GSE14548, and GSE54002)." (PMID 35534547, 2022). "Similarly, SOD2 expression was positively correlated with M2 macrophage infiltration in patients with basal-like aggressive breast carcinoma (p < 0.001), as validated by TIMER 2.0, a systematic analysis of tumor-infiltrating immune cells." (PMID 35017469, 2022).